KRAS (KRas proto-oncogene, GTPase)
Diseases named in the same sentence as KRAS in open-access papers (continued):
Sharing a sentence is not in itself a finding about the gene and the disease.
tumor (continued). "Since the discovery of the benefit of EGFR-targeted monoclonal antibody therapy in patients with KRAS wild-type metastatic colorectal cancer, it has become increasingly important to understand the mechanisms operating in tumours that eventually develop drug resistance." (PMID 21811251, 2011). "While the present trial requires that parameters of the EGFR-pathway are determined, KRAS mutation of the tumour does not affect treatment within the trial." (PMID 21861888, 2011). "PETACC-3, an adjuvant trial including patients with stage II to III colon cancer found KRAS mutation in 37% of cases, the incidence of which did not vary with tumor stage but was associated with grade." (PMID 24212832, 2011). "We recognise that there were a small number of KRAS mutant tumours available for comparison and this may have limited our analysis." (PMID 21385341, 2011). "No mutations were detected in either the EGFR gene or the KRAS gene in the primary tumor from this patient." (PMID 21414214, 2011). "A good example is the inherent resistance of tumours to anti-EGFR antibody and small molecule therapies resulting from the presence of a KRAS mutation and the sensitivity of patients to the gefitinib and erlotinib EGFR inhibitors in non-small cell lung cancer patients with activating EGFR mutations." (PMID 21649578, 2011). "The KRAS status of the lymph nodes in the other three patients showed heterogeneity, of which at least one lymph node metastases showed a different KRAS status compared with the primary tumour." (PMID 21364579, 2011). "Single-arm studies and large randomized studies on first-line and previously treated metastatic CRC patients have demonstrated KRAS tumor mutations to be predictive of a lack of response to the EGFR-targeted antibodies cetuximab and panitumumab." (PMID 24212797, 2011). "In our retrospective study, 26.7% of patients, all with KRAS wild-type tumours, who had previously unresectable liver-only metastases, underwent surgical resection after systemic therapy, with R0 resection achieved in 38 patients (21.6%); one of those was patient with the BRAF V600E mutation." (PMID 22933967, 2011). "On the other hand, the intratumoral heterogeneity of tumour tissues for KRAS gene status suggested that residual KRAS WT tumour cells may respond to cetuximab, but this idea is still under debate." (PMID 21730978, 2011). "The absence of difference in the degree of genomic abnormalities between KRAS mutant and wt tumours is interesting, as both our transcriptional and genomic data imply enhanced activity of genes involved in chromosome structure and organisation in KRAS mutant tumours." (PMID 21385341, 2011). "Histopathological characteristics of the primary tumour were comparable between patients with and without a KRAS mutation." (PMID 21364579, 2011). "In contrast, tumours driven by mutant KRAS were seen to be insensitive to NVP-BEZ235." (PMID 21649578, 2011). "Another explanation for the discordant results may be heterogeneity of KRAS status within the primary tumour, although this was the case in only a small number of patients." (PMID 21364579, 2011). "The patients with the KRAS mutation in codon 13 had a much lower treatment effect compared to the patients with wt-KRAS tumours and might have nevertheless benefited from treatment with cetuximab." (PMID 22933967, 2011). "In the second-line study, 597 patients with wild-type KRAS tumours were included." (PMID 21989186, 2011). "Therefore, the European Medicines Agency and the Food and Drug Administration have restricted the use of anti-EGFR antibodies in metastatic CRC to patients with KRAS wild-type tumours." (PMID 21364579, 2011).
tumor (continued). "However, at the time, very little is known about the interrelationship between TILs, MSI, and other tumour molecular features, such as the CpG island methylator phenotype (CIMP), global DNA hypomethylation, and KRAS, BRAF, and PIK3CA mutations." (PMID 22110523, 2011). "Particularly, the analysis of the PRIME trial showed that the patients with KRAS mutated tumours and moderate or severe skin rash presented better outcome in comparison with those with KRAS wt tumours and no or mild skin rash." (PMID 21283802, 2011). "Two patients showed heterogeneity of KRAS status within the primary tumour." (PMID 21364579, 2011). "We further found a previously undetected G12A substitution in exon 2 of KRAS in sample 11 (50% tumor cell content) and confirmed this mutation by subcloning of KRAS exon 2 amplicons and subsequent dideoxy sequencing (data not shown)." (PMID 21573178, 2011). "Mutational analysis can be performed by using tissue from either the primary tumor or a metastatic site, since high concordance has been observed between primary tumors and metastases for KRAS mutations in the majority of the studies published up to now." (PMID 22216189, 2011). "A number of genes demonstrated reduced copy number and expression in KRAS mutant tumours, including putative tumour suppressor genes (FOXO3, EXTL2, PPP2R1B), negative regulators of the receptor tyrosine kinase oncogenic pathways (PTPRK, DGKZ, NCAM1), and negative regulators of Ras (EPHB2)." (PMID 21385341, 2011). "We find that this RAS pathway signature is a high sensitivity but low specificity predictor of KRAS mutation status, as many cell line and tumor samples appear to have RAS pathway activation in the absence of mutations in KRAS." (PMID 20591134, 2010). "New evidence suggests that patients with KRAS, BRAF or PTEN mutations experience fewer clinical responses to these drugs, compared with patients with wild-type tumours; moreover, molecular analysis, particularly of KRAS, is routinely being performed in standard molecular pathology laboratories." (PMID 19935791, 2010). "Interestingly, mutant KRAS tumours have been shown to express high constitutive levels of MKP-1, MKP-2 and MKP-3, probably as part of the regulatory feedback loop to attenuate the high activation of ERK by mutant KRAS." (PMID 20234366, 2010). "The stimulatory effect of oncogenic KRAS on one or more of these transcription factors may explain why basal Noxa levels are low in KRASD13-deleted tumour cells." (PMID 20354524, 2010). "If the tumor has a small content of KRAS mutated cells, not detectable by DNA sequencing, anti-EGFR therapy probably fail to have an anti-proliferating effect on these cells." (PMID 21197450, 2010). "Sensitive methods are required to reliably detect KRAS mutations in tumor samples due to admixture with non-mutated cells." (PMID 21110880, 2010). "With respect to its predictive role, several retrospective analyses of tumour samples in CRC patients receiving anti-EGFR antibody treatment have shown that patients with mutated KRAS did not benefit from anti-EGFR therapy." (PMID 20959826, 2010). "However, it is also notable that the ratio of KRAS/PIK3A was lower in the lymph node compared to their primary tumor in 3 out of 4 samples." (PMID 20233444, 2010). "Therefore, treatment is only approved for patients harbouring a tumor with a wild-type (wt) KRAS gene." (PMID 21122130, 2010). "These factors may have included differences in the sensitivity and specificity of KRAS tests, differences in sample processing and DNA enrichment techniques between laboratories, and variation in tumor content between tumor samples and within tumor samples." (PMID 20398393, 2010).
tumor (continued). "In conclusion, our data show that EGFR GCN and KRAS mutation status are neither predictive nor prognostic factors for pathological tumour response and DFS in LARC patients treated with preoperative chemoradiation." (PMID 20842128, 2010). "Oncogenic KRAS may sensitise tumour cells to apoptosis induction by forcing cell-cycle progression in the presence of DNA damage." (PMID 20354524, 2010). "The lack of quantification of KRAS mutation alleles may deprive patients of a treatment, which could be targeted on tumor cells with intact KRAS gene." (PMID 21197450, 2010). "Treatments are selected largely without regard for tumour mutation profiles, although recent evidence linking KRAS mutation with poor response to EGFR mAb now influences decisions in the clinic." (PMID 19603024, 2009). "Other than reported previously, herein we tested the selectivity of KRAS-TMGB in routine clinical sample conditions, i.e., by serially diluting mutant samples with a high tumor cell content (70%) in KRAS wild-type tumor samples with the same DNA characteristics." (PMID 19888477, 2009). "None of patients with KRAS 61 or 146 mutated tumours responded, in comparison with 22 (37%) of 60 KRAS 61 and 146 wild-type patients (P=0.047)." (PMID 19603018, 2009). "Seven tumours carried both KRAS and PIK3CA mutations, whereas BRAF mutations did not co-occur with the others; these frequencies closely match those in published reports and were similar between the US and Greek cohorts." (PMID 19603024, 2009). "Likewise, small-molecule inhibition of MEK abrogated tumour growth more profoundly in BRAF-mutant than KRAS-mutant tumour xenografts." (PMID 19603024, 2009). "The availability of this dataset allowed us to determine whether the GEPR could predict response to alternate EGFR-targeted agents, employ the use of KRAS status to enrich the predictive power, and function across tumor types (CRC versus non-small cell lung)." (PMID 19439077, 2009). "Several commercial DNA sequencing-based KRAS tests for tumor tissues are available." (PMID 19386128, 2009). "Of interest, wild type KRAS may function as an inhibitor of tumorigenesis and thus represent a form of tumor suppressor gene." (PMID 19238210, 2009). "Among 87 patients of the study population, none of 21 patients with tumours presenting whatever mutation responded to the treatment, in comparison with 22 (37%) of 60 patients with KRAS 61 and 146 and BRAF wild-type disease (P=0.0005)." (PMID 19603018, 2009). "When comparing the expression difference between normal and tumour samples, we found significant underexpression of the DCN gene in the group of tumours with activating KRAS mutations in comparison with tumours without these mutations (p < 0.05)." (PMID 19678923, 2009). "It is tempting to suggest that specific KRAS and BRAF mutation interaction may have a role to modulate gene expression profiling in specific tumor types (either MSS, or MSI, or CIN) toward a more aggressive phenotype." (PMID 19087308, 2008). "In the present study ∼2 out of 3 of LKB1 mutant tumours were KRAS wild type." (PMID 18594528, 2008). "In our study, we were not able to detect a significant survival difference for patients whose tumours contained LKB1 mutations alone or concurrently with KRAS mutations (data not shown) likely because of the limited number of tumour specimens." (PMID 18594528, 2008). "Activating KRAS and BRAF mutations typically show mutant exclusivity in tumours." (PMID 19018267, 2008). "In this study, 8 out of 9 KRAS/BRAF mutations were identified in early stage (stage I, II) tumours." (PMID 19018267, 2008).
tumor (continued). "This study performed on 59 MCRC patients confirms that the presence of KRAS mutation in tumour is highly predictive of a non-response to treatment based on cetuximab plus chemotherapy in a series of 30 patients." (PMID 17375050, 2007). "This analysis focussed on secondary RDT end points: changes in bi-dimensional tumour measurements from baseline after 12 weeks and overall tumour responses (WHO criteria) at week 24, progression-free survival (PFS), safety and biomarkers (BRAF, KRAS and NRAS mutational status)." (PMID 16880785, 2006). "In summary, BRAF and KRAS mutations were mutually exclusive in the morphological characteristics of colorectal nonserrated neoplasias." (PMID 16404419, 2006). "Specifically, we highlight the interplay between KRAS signaling, the transcriptional coactivator YES1-associated protein (YAP) and Src family kinases (SFKs) in the pathogenesis of PDAC, including metabolic reprogramming and shaping of the tumor microenvironment." (PMID 41484057, 2026). "Using the IHC method on tumor front and center, the authors show that KRAS-mutated tumors have significantly lower infiltration of CD8+ cytotoxic T cells and T-bet+ Th1 cells compared with KRAS wild-type cases, particularly at the tumor front, where immune-tumor interactions are most critical." (PMID 41596586, 2026). "Background/Objectives: The KRAS rs61764370 T>G single-nucleotide polymorphism (SNP), located in a let-7 microRNA binding site within the 3' untranslated region (3'UTR) of the KRAS gene, may modulate tumor aggressiveness by altering post-transcriptional gene regulation." (PMID 41751217, 2026). "However, recent studies have revealed that some of these lesions, even without cytological dysplasia, may harbor somatic mutations associated with neoplasia, particularly in the GNAS and KRAS genes." (PMID 40964650, 2026). "The tumor was positive for the KRAS G12S mutation, and negative for the BRAF mutation." (PMID 41589237, 2026). "However, recent studies have highlighted the substantial heterogeneity within KRAS‐mutant tumors, suggesting that the presence or absence of co‐occurring mutations can significantly influence tumor behavior, prognosis, and therapeutic response." (PMID 41522471, 2026). "Furthermore, oncogenic KRAS might exacerbate oxidative stress and anabolic metabolism, potentially synergizing with KEAP1/STK11 co-mutations to drive tumor aggressiveness." (PMID 41541668, 2026). "Therefore, future studies might consider stratifying by the mutation status of different common tumour mutations in CRC, such as KRAS." (PMID 40968593, 2026). "Therefore, we explored the possibility that RNA-level events, such as alternative splicing, could modify KRAS activity and contribute to tumor progression." (PMID 41368203, 2026). "In patient 4, the KRAS mutation was found in the PDOs but not in the primary tumor material." (PMID 41141365, 2025). "Unlike TAAs, which may also be expressed in normal tissues, KRAS-derived neoantigens are tumor-specific, reducing the risk of off-target effects and making them highly attractive candidates for cancer immunotherapy." (PMID 40429703, 2025).
tumor (continued). "Oncogenic KRAS mutations lock the protein in its active state, resulting in persistent activation of downstream signaling cascades, such as the mitogen-activated protein kinase (MAPK) and phosphatidylinositol 3-kinase (PI3K) pathways, which drive tumor growth and progression." (PMID 40128846, 2025). "Resistance to these treatments frequently emerges from secondary KRAS mutations, activation of wild-type KRAS alleles, or compensatory signaling through co-expressed RAS isoforms (NRAS, HRAS) stimulated by growth factors prevalent in the tumor microenvironment (TME)." (PMID 41471277, 2025). "The differences in GNAS and KRAS mutational status and unique pathological behavior observed in the intestinal subtype support the potential driver role of GNAS in histopathological tumor development with unique outcomes that may promote GNAS status as an early prognostic marker itself." (PMID 40002298, 2025). "However, it remains unclear whether synergism between EGFR/KRAS mutations and FLCN LOH accelerates tumor progression in the lung." (PMID 40630489, 2025). "The mutational analysis of KRAS exon 2 identified a novel KRAS mutation in codon 232 (ENSFCAT00000019265.5:c.696A>T (p.Gln232His)) in two epithelial tumors of the follicular pattern (2/16, 13%), one TNA and one TWA, both presenting multiple tumor foci within the same thyroid lobe." (PMID 40711277, 2025). "Additionally, oncogenic KRAS has been demonstrated to facilitate SUMOylation-dependent release of extracellular vesicles and promote lymphangiogenesis, hence enhancing the interplay between intracellular oncogenic signaling and the tumor microenvironment." (PMID 41228299, 2025). "KRAS but not tumor suppressor mutations are found in LG PanINs." (PMID 40829181, 2025). "On the other hand, some studies have indicated that KRAS exon 3 mutations may present a less aggressive biological behavior than exon 2 mutations, as they were associated with a lower TNM stage and a less invasive tumor." (PMID 40575161, 2025). "Conversely, gene panels remain the predominant method for the detection of somatic driver mutations in tumor tissue, alongside WES in some institutions, given their high coverage of exonic regions where the majority of actionable alterations reside (e.g., EGFR, BRAF, PIK3CA, KRAS, BRCA1/2)." (PMID 41228293, 2025). "Additionally, oncogenic KRAS effector signaling reprograms tumor metabolism in ways that could be exploited for therapeutic benefit." (PMID 40829181, 2025). "Our patient has a KRAS mutation detected in the tumor tissue, but not in the blood sample." (PMID 40630489, 2025). "Taking in situ repair of single-gene mutations as an example, Sayed’s team used Prime Editor (PE3 system) to target correction of KRAS G12D mutation in a pancreatic cancer model, resulting in tumor growth inhibition of 55% without significant off-target effect." (PMID 40697666, 2025). "For example, miR-31 and miR-135b have both been implicated in the serrated neoplasia pathway—particularly in lesions with high microsatellite instability—high and BRAF mutations—whereas miR-143 and miR-145 are commonly associated with AD–carcinoma sequences and KRAS or APC mutations." (PMID 40693022, 2025). "Indeed, KRAS appears up-regulated in the tumor (log2FC: 1.47, adjusted P value: 3.34e-35)." (PMID 40523964, 2025).